NCOA1 (nuclear receptor coactivator 1)
Diseases named in the same sentence as NCOA1 in open-access papers (continued):
Sharing a sentence is not in itself a finding about the gene and the disease.
tumor (33 papers, 2004 to 2026). "Moreover, recent studies have indicated that TAMs and tumor-associated neutrophils (TANs) can also contribute to tumor cell egress and survival via NCOA1, CCL18, VCAM1, ICAM1 etc." (PMID 28591712, 2017). "The first was a group of novel genes and the second was a group of genes associated with various cancer and tumour diseases (TXNDC12, NRDC, MIR761, ITSN2, NCOA1, SCUBE2, DENND5A, RCN2)." (PMID 40003092, 2025). "UTROSCT is a unique neoplasm characterized by recurrent NCOA1-3 fusion genes." (PMID 37551382, 2022). "Interestingly, recurrent mutations of genes previously reported to be mutated in cancer: ABL1, BUB1B, NCOR1 (each mutated in three tumours), and CARS, HSP90AB1, NCOA1 (each mutated in two tumours) were uniquely found in recurrent/metastatic NPCs (n=33)." (PMID 28098136, 2017). "In conclusion, our results provide the first evidence that NCOA1 is a direct target of miR-105-1 suggesting that NCOA1 and miR-105-1 may have potential prognostic value and may be useful as tumor biomarkers for the diagnosis of HCC patients." (PMID 28060733, 2017). "Previous studies reported that miR-105 might target several mRNAs, such as mRNAs of SOX9, SUZ, and NCOA1, which are involved in tumor behavior and malignant progression." (PMID 29282124, 2017). "Taken together, our findings indicate that miR-105-1 levels may play an essential role in HCC progression by targeting NCOA1 suggesting that NCOA1 and miR-105-1 have potential prognostic value as tumor biomarkers in HCC patients." (PMID 28060733, 2017). "This explains why NCOA1 could enhance the transcriptional activity of the VEGFa promoter under both hypoxia and normoxia conditions and also implies a role of NCOA1 in upregulating VEGFa expression and tumor angiogenesis under both conditions." (PMID 26287601, 2015). "However, obesity-induced leptin and/or insulin resistance could thwart such tumor-suppressing activity by miR-4443 on TRAF4/NCOA1 and lead to potentiating the risks for CRC clinical presentation in obese individuals." (PMID 31007685, 2019). "For example, knockout of Ncoa1 influences fat oxidation and energy metabolism, which may complicate the correlation relationship between Ncoa1-promoted tumor angiogenesis and Ncoa1-influenced tumor growth." (PMID 26287601, 2015). "Specifically, HDAC4, HDAC5, KAT2B, NCOA1, SIRT1, and SIRT4 had lower expression in tumor tissues across 14, 12, 18, 17, 16, and 12 cancer types, respectively." (PMID 39906742, 2024). "Cyclin D1 enhances the activity of Erα by interacting with its co-regulators, SRC1 (NCOA1) and AIB1 (NCOA3), in tumor cells." (PMID 37427143, 2023). "It has been also demonstrated that the normal function of this tumor suppressor miRNA is to down-regulate a number of putative oncogenes including validated miR-22 targets MAX, MYCBP, HDAC4, HDAC6, CDK6, CDKN1A and NCoA1." (PMID 29716630, 2018). "We further demonstrate that normal function of this tumor suppressor microRNA is to down-regulate a number of putative oncogenes including validated miR-22 targets MAX, MYCBP, HDAC4, HDAC6, CDK6, and NCoA1." (PMID 26244872, 2015). "However, the present known targets of miR-105 are mainly those involved in tumor behavior and malignant progression such as mRNAs of SOX9, SUZ, and NCOA1." (PMID 29282124, 2017). "Additionally, to sustain proliferative signalling (right side), the tumour oncogene CCND1, probably influenced by the co-expressed gene NCOA1/3 as well as the suppressors CDKN2A and CDKN2B, which govern the cell cycle, were genetically altered to enhance cancer cell growth in both smoking subgroups." (PMID 32455963, 2020).
cancer (30 papers, 2008 to 2026). A tumor composed of atypical neoplastic, often pleomorphic cells that invade other tissues. "Notably, genes such as NCOA1 and SDHB are identified as being associated with cancer susceptibility." (PMID 40724918, 2025). "Downregulation of other cancer-promoting molecules such as HDAC6, required for efficient oncogenic tumorigenesis, and NCoA1, whose overexpression increases the number of circulating cancer cells and the metastasis, may overwhelm PTEN’s efficacy in this case." (PMID 35744941, 2022). "Especially, Ncoa1 knockout mice grow well and show a normal life span, supporting the notion that NCOA1 may be a preferential cancer target with tolerable adverse effect." (PMID 26287601, 2015). "For instance, NCoA1 protects cancer cells from tamoxifen induced apoptosis." (PMID 26244872, 2015). "Interestingly, the major clinical importance of an increased expression of NCoA1 in patients with advanced cancer relates to the development of drug resistance." (PMID 26244872, 2015). "Transfection of malignant T cells with recombinant miR-22 inhibits the expression of validated miR-22 targets including NCoA1, a transcriptional co-activator in others cancers, as well as HDAC6, MAX, MYCBP, PTEN, and CDK2, which have all been implicated in CTCL pathogenesis." (PMID 26244872, 2015). "Interestingly, our panel included genes already described to be cancer predisposition genes (FAS, ITK, KIF1B, PGR and MET) or previously reported as playing important roles in cancer (ABI1, ARID5B, DNMT3A, HEY1, KDM5C, NCOA1, NUP98, and SLC34A2), or in DNA repair process (FANCF)." (PMID 30925779, 2019). "This overexpression of NCOA1 in MCF-7 cells resulted in heightened expression of Cyclin D1 and VEGF, two established target genes regulated by STAT3 in several cancer types." (PMID 41562922, 2026). "NCOA1 and NCOA3 are overexpressed in human breast cancer, and their inhibition or deletion has attenuated cancer progression in various models of multiple types of cancer." (PMID 40023399, 2025). "According to the results of the analysis of malignant tumors, NCOA1, HERC1, HIPK3, MBNL1, hsa-let-7b-3p, hsa-miR-378a-5p, and hsa-miR-26a-5p were predictive or prognostic factors for malignant tumors." (PMID 33841514, 2021). "In the CHRNB4-high subgroup, CHRNB4 was co-expressed with numerous genes, such as ADCY9, NOTCH3, ARNT, NCOA1, and NCOA3, which correlated with multiple cancer-related processes, but only one gene, FLT4, was co-expressed in the CHRNB4-low subgroup." (PMID 32455963, 2020). "Among the top-scored predicted targets of miR-4443, NCOA1 and TRAF4 have known roles in cell migration and cancer metastasis, and were chosen for validation." (PMID 27842582, 2016). "NCOA1 and CBL have previously been shown to play oncogenic roles in many cancers." (PMID 37373553, 2023). "Notably, the RXRA protein was in protein complexes with RARA, PPARG, NCOA1, NCOA2, and NCOR2 cancer drivers." (PMID 29572294, 2018). "Cancer cell type specific co-regulators included SP1, NCOA1, NCOA2, and PIAS1." (PMID 28117763, 2017). "Moreover, leptin and miR-4443 transfection significantly down-regulated endogenous NCOA1 and TRAF4, both predicted targets of miR-4443 with known roles in cancer metastasis." (PMID 27842582, 2016).
bacterial infection (1 paper, 2020). "This study was also the first to report that NCOA1 and NCOA2 were negatively associated with PCT in the serum (a validation factor predicts bacterial infection)." (PMID 32884936, 2020). "This probably shows that NCOA1 and NCOA2 might be protective factors against bacterial infection." (PMID 32884936, 2020).
NCOA1 also shares sentences with these, for which no sentence is quoted: endometriosis (4 papers); glioblastoma (2); Infertility (2); leukemia (2); mesenchymal chondrosarcoma (2); uterine sarcoma (2); alveolar rhabdomyosarcoma (1); atherosclerosis (1); autism (1); Bardet-Biedl syndrome (1); brain tumor (1); ciliopathy (1); clear cell sarcoma of the kidney (1); CNS tumors (1); dementia (1); diabetes (1); endometrial cancer (1); gastric cancer (1); glioma (1); Hypertension (1); hypothyroidism (1); infection (1); inflammatory myofibroblastic tumor (1); Lipedema (1); lipoma (1); metabolic disorders (1); metastatic tumors (1); pancreatic cancer (1); prostate (1); psychiatric disorder (1).
A further 5 diseases each share a sentence with NCOA1 in 1 paper.